CD38 (CD38 molecule)
Diseases named in the same sentence as CD38 in open-access papers (continued):
Sharing a sentence is not in itself a finding about the gene and the disease.
Insulin resistance (7 papers, 2015 to 2023). Increased resistance towards insulin, that is, diminished effectiveness of insulin in reducing blood glucose levels. "Furthermore, the insulin resistance was also significantly improved in CD38-deficient mice fed with HFD plus STZ compared with CD38flox mice." (PMID 37958991, 2023). "NAM is also a feedback inhibitor of NAD+-dependent enzymes, and high concentrations of NAM inhibit the activity of poly (ADP-ribose) polymerase (PARP), sirtuins, and CD38, resulting in an increase in accumulation of hepatic fat, insulin resistance, and spatial-learning deficits." (PMID 38201974, 2023). "However, more experiments are needed to explore the mechanism of CD38's role in the relationship between NAFLD and insulin resistance." (PMID 36794157, 2023). "First, the pathogenesis of CD38 in NAFLD has not been adequately studied, and more studies are needed to demonstrate the correlation between CD38 and inflammation, abnormal accumulation of fatty acids, and insulin resistance." (PMID 36794157, 2023).
metabolic syndrome (7 papers, 2011 to 2025). A cluster of metabolic risk factors for CARDIOVASCULAR DISEASES and TYPE 2 DIABETES MELLITUS. "The authors showed that CD38 is a crucial target site for controlling metabolic syndrome and found that apigenin acts as a CD38 inhibitor." (PMID 34679777, 2021). "In addition, NAD+-boosting compounds such as inhibitors of PARP and CD38 have been studied as therapeutics for treatment of mitochondrial diseases and metabolic syndrome." (PMID 30026729, 2018). "Because aging, diet-induced oxidative stress and mitochondrial dysfunction are associated with an NAD+ deficit, we were interested in examining the effect of elevating tissue NAD+ via genetic ablation of CD38 on the pathogenesis of diet-induced metabolic syndromes and on exercise performance." (PMID 26287487, 2015). "Thus, apigenin appears to be a CD38 inhibitor that may be used as a promising strategy for the treatment of metabolic syndrome via activation of NAD+ and SIRT1." (PMID 34679777, 2021).
myeloid malignancies (7 papers, 2019 to 2025). "CAR-engineered NK (CAR-NK) cell-based therapy has been developed pre-clinically to treat myeloid malignancies, targeting antigens such as CD38 and CD12322,112,113." (PMID 39893165, 2025). "The following surface antigens were selected for analysis: for myeloid tumors: MV-4-11, Thp-1, HL-60—CD11b, CD14, K562 and KG-1—CD34, and CD38; for lymphoid neoplasms: Raji, Daudi, U2932—CD19, CD20, Jurkat—CD4, CD8." (PMID 35053549, 2022). "Recently, it has been demonstrated that it is a specific marker expressed on LSCs of CML, both in BM and PB samples, and absent on CD34+/CD38− stem cells in normal subjects or on LSCs of other myeloid neoplasms." (PMID 35205639, 2022). "In this tissue, CD38+ and CD14+ antibody staining is not strictly restricted to single lineages, and these markers can be aberrantly expressed in myeloid neoplasms included in this data set." (PMID 36959190, 2023).
neuroblastoma (7 papers, 2013 to 2025). Neuroblastoma (NB) is the most common solid, extracranial childhood tumor. "Small molecule inhibitors of CD38 promote increases in interferon gamma and stimulate natural killer cell proliferation for the treatment of neuroblastoma." (PMID 36845935, 2023). "We also observed a higher proportion of terminally exhausted and dysfunctional CD8+ T cells (PD1+CD38+) after anti-PD1 treatment in idMMR neuroblastoma tumors." (PMID 36068918, 2023). "We also observed an increase of activated CD4+ T cells (CD38+CD4+ T cells) with higher cytotoxic function (CD107a+ CD4+ T cells) in the spleens of previously cured mice that were rechallenged with the poorly immunogenic pMMR neuroblastoma tumor cells." (PMID 36068918, 2023). "Our group has recently carried out two different sets of studies aimed to characterize the expression and function of CD38, along with other ecto-enzymes, on EVs isolated from patients with MM and neuroblastoma (NB)." (PMID 31783629, 2019). "None of the other markers tested (e.g. CD99, CD38, CD19, CD20, CyCD79a, CD34, numyogenin, nuMYOD1) was expressed by neuroblastoma cells." (PMID 23472067, 2013).
ZIKV infection (7 papers, 2017 to 2026). "To identify which NADases contribute to the loss of NAD+ homeostasis during ZIKV infection, we analyzed the mRNA expression of Sarm1, Cd38, and Cd157 in the brains of ZIKV-infected neonate mice over the course of infection." (PMID 41362627, 2025). "Here, we show that CD38 expression on activated immune cells, including macrophages and lymphocytes, seems to be a hallmark of ZIKV infection." (PMID 41362627, 2025). "We first evaluated markers predictive of acute ZIKV infection compared to healthy samples, which confirmed elevation of CD38, Fas Ligand, CD69, Ki67, and perforin as observed in our analysis of mean signal intensity." (PMID 41000887, 2025). "In our study, CD38 upregulation emerges as a late-stage event during ZIKV infection in the brain, coinciding with the decline in NAD+ levels, but not with the peak of viral replication." (PMID 41362627, 2025). "Our data reveal a temporal dissociation between CD38 mRNA upregulation, protein induction, and enzymatic activity during ZIKV infection." (PMID 41362627, 2025). "Although we demonstrated that CD38 is responsible for NAD+ depletion in the later stages of ZIKV infection in mice, the functional consequences of this event—such as potential neurological or cognitive dysfunction—remain to be determined in future studies." (PMID 41362627, 2025). "Another important surface marker that we found to be upregulated in multiple cell types within PBMCs upon ZIKV infection is CD38." (PMID 34160241, 2021). "The impact of ZIKV infection on T-cell activation was evaluated by analyzing the expression of activation markers CD38 and HLA-DR on CD8, CD4 and on DN T-cells." (PMID 28740159, 2017). "In addition to the lymphoid infiltrate, CD11b+TMEM119- macrophages also showed elevated CD38 levels, in line with their increased accumulation during ZIKV infection, suggesting functional activation and a potential role in NAD+ consumption." (PMID 41362627, 2025). "Therefore, CD38 is the main NADase expressed at later stages of ZIKV infection in the brain and likely drives the disturbance in NAD+ levels in this context." (PMID 41362627, 2025). "CD38 is known to be upregulated in inflammatory conditions, raising the hypothesis that neuroinflammation during ZIKV infection could contribute to NAD+ imbalance." (PMID 41362627, 2025). "The correlations unique to acute ZIKV infection (e.g., positive correlations in the proportion of CD38+ pDCs and CD38+ Th1 CD4+ T cells, or between CD40+ cDCs and Ki-67+ DN B cells) may reflect interactions that are essential to mount a productive antiviral immune response." (PMID 35584677, 2022). "During the acute phase of ZIKV infection, the number of specific innate and adaptive cell types temporarily increased, including intermediate CD14+CD16+ monocytes, CD69 + NK, HLA‐DR+CD38+ non‐naïve CD8+ T cells, Th1 CD4+ T cells, and Tbet+ plasma cells." (PMID 41556482, 2026). "We found that CD38, CD69, Fas Ligand, perforin, Ki67, and FcRγ expression was upregulated on NK cells during acute ZIKV infection, suggesting NK cells are activated, proliferating, and potentially cytotoxic during acute infection." (PMID 41000887, 2025). "Acute ZIKV infection was accompanied by a profound accumulation of cycling, activated non-naïve CD8+ T cells co-expressing HLA-DR and CD38." (PMID 35584677, 2022).
acute kidney injury (6 papers, 2020 to 2026). Sudden and sustained deterioration of the kidney function characterized by decreased glomerular filtration rate, increased serum creatinine or oliguria. "Given these recent excellent results, CD38 antibody combinations with Vd or VCd should strongly be considered in any patient with acute renal failure due to cast nephropathy." (PMID 41134013, 2026). "Previous studies reported that blocking CD38 significantly inhibited LPS-induced NF-κB pathway activation and M1 polarization of macrophages, alleviating LPS-induced acute kidney injury in mice." (PMID 36998049, 2023). "A role for CD38 in LPS-induced acute kidney injury was suggested using quercetin, a dietary flavonoid that inhibits the NADase activity of CD38." (PMID 31963337, 2020). "In addition, in CD38 KO mice, there is increased TLR4 expression compared to WT mice, which favors the overexpression of IFN-γ and acute kidney injury." (PMID 41488275, 2025).
Cognitive impairment (6 papers, 2021 to 2026). Abnormal cognition is characterized by deficits in thinking, reasoning, or remembering. "It has been shown that Cd38 knockout AD mouse models have attenuated cognitive deficits and decreased cerebral amyloid burden, and that primary neurons cultured from those mice secrete significantly less Abeta species." (PMID 32878879, 2021). "Future directions should include investigation of CD38 expression patterns in human choroid plexus across the lifespan, assessment of CSF NAD+ levels in aging and cognitive impairment, and development of additional brain-penetrant CD38 inhibitors with improved pharmacological properties." (PMID 41542058, 2026). "Following intervention with the CD38 inhibitor in APP/PS1 mice, the energy metabolism disorder was improved in the hippocampus and cortex, the level of proinflammatory cytokines was reduced, and cognitive impairment was improved." (PMID 35241173, 2022).
depression (6 papers, 2016 to 2024). "The CD8 + HLA-DR + CD38 + T cells that have been linked in this study to LN, C3 depression, and SLE disease activity are believed to be the cause of SLE's persistent immune activation." (PMID 38650001, 2024). "In the present study, based on the associations between CD38 genetic variation and affective reactivity, social anxiety, and depression, we examined the relationship between amygdala-sgACC connectivity and neuroticism in individuals with varying levels of social anxiety and depression." (PMID 32116489, 2020). "The current study examined the moderating role of CD38 genetic variants (rs3796863 and rs6449182) that have been associated with enhanced (or reduced) social sensitivity on neural activation related to neuroticism, which is commonly elevated in individuals with social anxiety and depression." (PMID 32116489, 2020). "This analysis was also conducted controlling for depression scores as a covariate and the CD38 genotype × Trauma interaction in predicting suicidal ideation remained significant, p < 0.01." (PMID 27486392, 2016). "In effect, the relation between CD38 genotype and trauma in predicting suicidal ideation occurred above and beyond the influence of depression." (PMID 27486392, 2016). "It was observed in the current study that individuals with the AA genotype for the CD38 SNP reported greater depression and suicidal ideation compared to C carriers." (PMID 27486392, 2016). "Moreover, the severe and fatal cases displayed profound T cell, and particularly CD8 T cell, depression, but an unusual presence of activated CD38+ HLA-DR+ CD8 T cells." (PMID 32957548, 2020). "In addition to somewhat elevated levels of depression and increased suicidal ideation, individuals with the AA genotype for the CD38 SNP also reported greater feelings of alienation from both parents and peers." (PMID 27486392, 2016). "Given the relationship between oxytocin and both depression and suicidality, in the current investigation it was hypothesized that genetic variants of the OXTR SNP rs53576 and the CD38 gene SNP rs3796863 would be related to depression and suicidal ideation among young adults." (PMID 27486392, 2016). "As in the case of the CD38 SNP, it was of interest to examine whether an OXTR genotype × Trauma interaction would predict depression and suicidal ideation scores." (PMID 27486392, 2016). "Interestingly, the relationship between the AA genotype of the CD38 SNP and experiences of trauma on suicidal ideation was not recapitulated in relation to depression." (PMID 27486392, 2016). "As well, there were no Sex × CD38/OXTR genotype interactions in relation to peer or parental alienation, suicidal ideation or depression scores." (PMID 27486392, 2016).
Immunodeficiency (6 papers, 2016 to 2025). Failure of the immune system to protect the body adequately from infection, due to the absence or insufficiency of some component process or substance. "Notably, we found that the elevated CD38 expression on B cells is a key factor driving B cell senescence, mitochondrial dysfunction, and increased transitional B cell proportion, contributing to the observed immunodeficiency, such as diminished serum antibodies." (PMID 41626283, 2025). "However, the knowledge about CD38 in HIV infection is currently inconclusive as to whether it is a player independent of viral replication that mediates immunodeficiency and disease progression or is a by-product of T cell activation." (PMID 33820568, 2021).
liver disease (6 papers, 2012 to 2026). "CD38 also plays a critical role in many liver diseases such as glucagon-induced gluconeogenesis in hepatocytes and lipopolysaccharide- (LPS-) induced acute damage of the liver." (PMID 33860064, 2021). "And in inflammatory liver disease, the CD38/NAADP-mediated Ca2+ signaling pathway is a potential novel therapeutic target." (PMID 33860064, 2021). "CD38/NAADP-mediated Ca2+ signaling pathway is a potential novel therapeutic target against inflammatory liver diseases." (PMID 28386045, 2017). "Hence, up-regulating the autophagic pathway by CD38/NAADP might be an attractive therapeutic strategy in inflammatory liver diseases." (PMID 28386045, 2017). "In our study, activated HLA-DR+CD38+ T cells were increased in comparison with levels of HIV mono-infected patients and healthy subjects reported in literature, and yet they failed significant association with HCV genotypes, liver disease and virological response to anti-HCV treatment." (PMID 22363790, 2012). "The CD19+CD24+CD38− primarily memory B cells were generally less in the diabetic than the non-diabetic groups irrespective of the liver disease stage." (PMID 33230233, 2020).
lung adenocarcinoma (6 papers, 2021 to 2024). A carcinoma that arises from the lung and is characterized by the presence of malignant glandular epithelial cells. "In the present study, we aimed to delineate the molecular and biochemical function of the tumor-associated CD38 in lung adenocarcinoma progression." (PMID 34226519, 2021). "It remained unknown whether the expression of tumor CD38 was associated with the prognosis of lung adenocarcinoma patients." (PMID 34226519, 2021). "CD38 on CD8+ cytotoxic T cell, NK cell, or regulatory T cell express higher levels of CD38 in SCLC compared to lung adenocarcinoma." (PMID 38533509, 2024). "Consistent with our findings, Moss laboratory utilized the CRISPR/Cas9 gene knockout of CD38 in A549 lung adenocarcinoma cells, which inhibited cell growth, cell invasion, and xenograft tumor growth in nude mice." (PMID 38545257, 2024). "Taken together, these results indicated that CD38 revealed a poor survival of the lung adenocarcinoma patients." (PMID 34226519, 2021). "We identified that the expression of CD38 was related to a potentiality of metastasis but a shortened survival in lung adenocarcinoma." (PMID 34226519, 2021). "Here we employed tissue microarrays of lung adenocarcinoma specimens to analyze CD38 expression by immunohistochemically staining (Seville Biology Company (Wuhan, China), Chort No.1601)." (PMID 34226519, 2021). "In addition, the frequency of CD38 on regulatory T cells or natural killer cells was significantly higher in treatment-naïve SCLC samples as compared to lung adenocarcinoma." (PMID 38533509, 2024). "Moreover, CD8+ T cell function was found to be inhibited by CD38-mediated adenosine production, and anti-PD-L1 and CD38 combination therapy synergistically inhibited the growth of murine lung adenocarcinoma tumors." (PMID 37842241, 2023). "Interestingly, we found that frequency of CD38 on CD8+ cytotoxic T cells or on monocytes/macrophages was significantly higher in treatment-naïve SCLC samples as compared to normal tissues or treatment-naïve lung adenocarcinoma." (PMID 38533509, 2024).
lupus nephritis (6 papers, 2018 to 2025). Glomerulonephritis in the context of systemic lupus erythematosus. "We next examined the effect of CD38 deficiency on the induction of lupus nephritis by evaluating glomerular cellularity at 12- and 16-weeks post-pristane treatment." (PMID 29463868, 2018). "Therefore, the CD38 monoclonal antibody (such as daratumumab, Isatuximab) becomes a new treatment option for membranous nephropathy, lupus nephritis, renal transplantation, and other refractory kidney diseases." (PMID 38799465, 2024). "It has been suggested that daratumumab may have additional effects such as blocking T cells co-expressing CD38 which are responsible for lupus nephritis and depleting plasmacytoid dendritic cells, also expressing elevated levels of CD38, hence reducing interferon type I activity." (PMID 38893662, 2024). "Moreover, it has been observed that lupus nephritis (LN) patients have an increased number of macrophages, whose CD38 expression is specifically activated and up-regulated, suggesting that CD38 might contribute to the regulation of LN development and progression by influencing immune responses." (PMID 39995666, 2025). "Since reduced numbers and/or functions of iNKT cells have been shown to exacerbate pristane-induced lupus nephritis, we assessed whether the absence of ART2 or CD38 had any influence on the frequency of CD1dhiCD5+ B cells in the spleen of mice treated with pristane." (PMID 30257456, 2018).
nonalcoholic fatty liver disease (6 papers, 2021 to 2025). "As examples, the present commentary tries to integrate responses of AHR and NAD+-consuming enzymes (PARP7/TiPARP, CD38 and sirtuins) into infectious and stress-induced inflammatory responses, the latter exemplified by nonalcoholic fatty liver disease (NAFLD)." (PMID 34559251, 2021). "Histological analysis also revealed that steatosis (score 0–3), hepatocyte ballooning (score 0–2), and lobular inflammation (score 0–3), as estimated by the nonalcoholic fatty liver disease activity score (NAS), were alleviated in CD38 vaccine mice relative to KLH mice." (PMID 40557469, 2025). "Studies have shown that by inhibiting the expression of CD38 and increasing NAD+ concentration, SIRT3 concentration can be increased to clear ROS and reduce lipid accumulation, thereby inhibiting the development of non-alcoholic fatty liver disease." (PMID 38862726, 2024).